NLRP3 (NLR family pyrin domain containing 3)
Diseases named in the same sentence as NLRP3 in open-access papers (continued):
Sharing a sentence is not in itself a finding about the gene and the disease.
Crohn disease (68 papers, 2009 to 2025). A gastrointestinal disorder characterized by chronic inflammation involving all layers of the intestinal wall, noncaseating granulomas affecting the intestinal wall and regional lymph nodes, and transmural fibrosis. "To date, caspase-1 is the most widely studied cysteine protease that regulates the pyroptosis pathway via inflammasome NLRP3 activation, which has been associated with susceptibility to Crohn’s disease." (PMID 36120344, 2022). "Genetic variations in a predicted regulatory region of the NOD-like receptor pyrin domain containing 3 (NLRP3) gene locus have been associated with an increased risk to develop Crohn’s disease (CD)." (PMID 34344313, 2021). "Genetic variations within the regulatory region of the gene encoding NOD-like receptor pyrin domain containing 3 (NLRP3) have been associated with Crohn’s Disease (CD)." (PMID 34344313, 2021). "Single-nucleotide polymorphisms of human NLRP3 gene have been related with susceptibility to Crohn's disease and the IL-18 cytokine has been shown to contribute to intestinal epithelial cell regeneration to chronic inflammation in IBD." (PMID 29416724, 2018). "Of particular importance is the discovery that increased NLRP3 inflammasome activity occurring because of loss of CARD8 inhibition of the inflammasome can be a cause of Crohn's disease which responds only to treatment involving IL-1β inhibition." (PMID 30455704, 2018). "NLRP3 gene mutations are also observed to be associated with rheumatoid arthritis, Crohn's disease, and abdominal aortic aneurysms." (PMID 29850543, 2018). "This discovery suggests the need for further studies to determine the frequency of excess IL-1β secretion in Crohn's disease patient populations due to CARD8 mutations or other abnormalities of the NLRP3 inflammasome." (PMID 30455704, 2018). "Furthermore, mutations in the downstream regulatory region of NLRP3 have also been shown to be associated with decreased IL-1β expression and increased susceptibility to Crohn’s disease (CD) in humans." (PMID 40227443, 2025). "In addition, a study on the association between NLRP3 and Crohn’s disease reported that a loss-of-function CARD8 missense mutation promotes NLRP3 inflammasome activation." (PMID 39201704, 2024). "NLRP3 inflammasome, as a major element in innate immunity, may protect against Crohn’s disease because a loss-of-function in NLRP3 was closely associated with the development of Crohn’s disease." (PMID 37833958, 2023). "In conclusion, our study identified the dysregulations of NLRP3 inflammasome-related genes and their associations with the immune landscape, subtypes of patients, phenotype-related hub genes, and potential drugs of Crohn’s disease." (PMID 36685554, 2022). "In addition, a recent study has shown that dysfunctional CARD8 mutations can also activate the NLRP3 inflammasome and contribute to the occurrence of Crohn's disease." (PMID 32148650, 2020). "Polymorphisms in the NLRP3 gene are associated with Crohn’s disease although the effect size of this may be small." (PMID 29515999, 2018). "Furthermore, polymorphisms of the NLRP3 gene lead to hypo-production of IL-1β that is associated with increased risk of developing Crohn’s disease." (PMID 28824627, 2017). "Additionally, polymorphisms in the Nlrp3 gene are associated with an increased susceptibility to Crohn's disease." (PMID 26484345, 2015). "The NLRP3 region was recently reported to be associated with Crohn's disease (CD) susceptibility." (PMID 19784369, 2009). "Furthermore, a study suggested that the occurrence of missense mutation in the CARD8 gene could activate NLRP3 inflammasome to affect Crohn’s disease." (PMID 37833958, 2023). "Notably, NLRP3 inflammasome has been shown to be closely associated with Crohn's disease." (PMID 31885813, 2019).
Crohn disease (continued). "This interaction induces the upregulation of caspase-1, IL-1β, NLRP3, ASC, and cleaved N-terminal GSDMD expression, activating NLRP3 inflammasome-mediated cell pyroptosis and impairing autophagy, ultimately exacerbating Crohn’s disease (CD)." (PMID 40001550, 2025). "The role of NLRP3 inflammasome in Crohn’s disease remains controversial, since its activation can protect intestinal epithelium by maintaining homeostasis, or aggravates intestinal damage via enhancing inflammation." (PMID 36685554, 2022). "Researchers have indicated that single-nucleotide polymorphisms in the NLRP3 gene are associated with susceptibility to UC, and NLRP3 inflammasome activity is increased in some patients with UC and Crohn’s disease." (PMID 35330829, 2022). "NLRP3 inflammasome was reported to participate in the pathogenesis, progression and treatment response of Crohn’s disease." (PMID 36685554, 2022). "Using unsupervised K-mean consensus clustering, we identified two subtypes of Crohn’s disease based on the 14 NLRP3 inflammasome-related genes." (PMID 36685554, 2022). "Our study reveals that the significance of NLRP3 inflammasome-related genes in Crohn’s disease, and provide insights to disease development and progression." (PMID 36685554, 2022). "In the present study, we investigated and evaluated the role of NLRP3 inflammasome-related genes in the pathogenesis of Crohn’s disease." (PMID 36685554, 2022). "Our findings provide a comprehensive overview of NLRP3 inflammasome-related genes in the etiology and promising possibilities for the treatment of Crohn’s disease." (PMID 36685554, 2022). "Classification of Crohn’s-disease samples based on NLRP3 inflammasome-related genes with ConsensusClusterPlus." (PMID 36685554, 2022). "Taken together, our findings indicate that NLRP3 inflammasome-related genes are involved in the immune regulation of Crohn’s disease." (PMID 36685554, 2022). "In this study, we aimed to provide a comprehensive overview of NLRP3 inflammasome-related genes and pathways in Crohn’s disease by a computational approach." (PMID 36685554, 2022). "Previous studies have shown that Herb-partitioned moxibustion treating (at Qihai (CV 6) and Tianshu (ST 25)) prevented the excessive activation of the NLRP3 inflammasome and repaired damaged colonic mucosa in Crohn’s disease." (PMID 34043726, 2021). "Crohn’s disease is a chronic inflammatory bowel disease and the NLRP3 inflammasome plays an important role in Crohn’s disease." (PMID 34043726, 2021). "In AMI, SLE, IBD, Crohn's disease, bacterial infections, eye diseases, etc., the NLRP3 inflammasome plays a critical role in regulating pathological processes." (PMID 32148650, 2020). "Special emphasis has been given to the susceptibility to Crohn's disease, in association with abnormalities in the NOD2 and in the NLRP3/inflammasome." (PMID 25821356, 2015). "Mutations in the genes encoding NLRP3 or NLRP12 lead to hereditary periodic fever syndromes, while mutations in CARD15 that encodes NOD2 are linked to Crohn’s disease or Blau’s syndrome." (PMID 24137163, 2013). "In addition, abnormal NLRP3 inflammasome activity has been identified as a key factor in the pathogenesis of Crohn’s disease and chronic gastritis." (PMID 38918852, 2024). "Although the role of the NLRP3 inflammasome in Crohn’s disease is debatable, our study reveals that the higher expressions of NLRP3 inflammasome-related genes were correlated with generally enhanced immune cell infiltration, immune-related pathways and human leukocyte antigen (HLA)-gene expressions." (PMID 36685554, 2022). "Recently, a study in patients with Crohn’s disease demonstrated a link between the activation of the platelet NLRP-3 inflammasome and the observed platelet hyperactivity and increased risk of thrombosis, further encouraging that NLRP-3 inflammasome activation in platelets promotes coagulation." (PMID 35979369, 2022).
Crohn disease (continued). "The expressions of NLRP3 inflammasome-related genes are generally upregulated in Crohn’s disease samples, and the gene-based signature could assist in the diagnosis of Crohn’s disease." (PMID 36685554, 2022). "The role of the NOD-like receptor family, pyrin domain-containing 3 (NLRP3) inflammasome in Crohn’s disease remains largely unknown." (PMID 36685554, 2022). "Our findings indicate that NLRP3 inflammasome and its related genes could regulate immune cells and responses, as well as involve in the pathogenesis of Crohn’s disease from transcriptomic aspects." (PMID 36685554, 2022). "Moreover, consensus clustering identified two Crohn’s disease clusters based on NLRP3 inflammasome-related genes, and cluster 2 was with higher expressions of the genes." (PMID 36685554, 2022). "This study for the first time identifies the mechanism by which herb-partitioned moxibustion (at CV 6 and ST 25) may inhibit the abnormal activation of the NLRP3 inflammasome by inhibiting the P2X7R-Pannexin-1 signaling pathway in Crohn’s disease rats." (PMID 34043726, 2021). "Gain-of-function polymorphisms in the NLRP3 inflammasome resulting from gene polymorphisms such as NLRP3 (Q705K) and loss-of-function in relation to CARD8 (C10X) are associated to RA and Crohn’s disease, and some evidence for a combined effect of these polymorphisms have been described." (PMID 30816317, 2019). "Patients with CARD8 mutations and excessive IL-1β production leading to Crohn's disease are in principle similar to patients with IL-10 abnormalities since in both cases increased NLRP3 inflammasome hyperactivity is due to lack of an inflammasome inhibitor." (PMID 30455704, 2018). "Hypoxia significantly reduces tumor necrosis factor α, interleukin (IL)-6 and NLRP3 expression, and increases the turnover of the autophagy protein p62 in colon biopsies of Crohn’s disease patients, and in samples from dextran sulfate sodium-treated mice and Il-10−/− mice." (PMID 28740109, 2017). "In humans, the role of NLRP3 in Crohn’s is equally confusing; polymorphisms associated with NLRP3 were shown to contribute to susceptibility to Crohn’s disease, but did not replicate in a separate study." (PMID 24381573, 2013). "Therefore, our findings indicate that NLRP3 inflammasome and its related genes could regulate immune cells and responses, as well as involve in the pathogenesis of Crohn’s disease." (PMID 36685554, 2022). "Crohn’s disease (CD) involves activation of mast cells (MC) and NF-кB in parallel with the PPAR-α/NLRP3 inflammasome/IL-1β pathway in the inflamed colon." (PMID 38283356, 2023). "The activation of NLRP3, as well as of its downstream effectors GSDMD, IL-1β and IL-18, is proportional to the severity of intestinal lesions manifested in Crohn’s disease." (PMID 37891577, 2023). "Using the DGIdb database, four key NLRP3 inflammasome-related genes (APP, HSP90AB1, NFKB and TLR4) were further selected as potential druggable targets for Crohn’s disease treatment." (PMID 36685554, 2022). "While this was not shown to be explicitly NLRP3 dependent, it is reasonable to speculate given that one study has demonstrated hyperactivation of NLRP3 in Crohn’s Disease patients (60%) as compared to healthy controls (28.6%)." (PMID 36581211, 2023). "However, a comprehensive overview of NLRP3 inflammasome and its related molecules in Crohn’s disease is lacking." (PMID 36685554, 2022).
acute lung injury (66 papers, 2015 to 2026). A condition of lung damage that is characterized by bilateral pulmonary infiltrates (pulmonary edema) rich in neutrophils, and in the absence of clinical heart failure. "The mechanism of cell pyroptosis caused by the TXNIP/NLRP3 signal axis has been reported in other diseases, such as intestinal ischemia-reperfusion injury, cadmium-induced liver injury, and LPS-induced acute lung injury." (PMID 38069134, 2023). "Fortunellin attenuated lipopolysaccharide (LPS)‐stimulated acute lung injury (ALI) through repressing the Toll‐like receptor 4 (TLR4)/nuclear factor kappa‐B (NF‐κB)/NLR Family Pyrin Domain Containing 3 (NLRP3) pathway." (PMID 38501503, 2024). "Our recent research proved that HSF1 was involved in the activation of the NLRP3 inflammasome in septic acute lung injury (ALI)." (PMID 36741074, 2023). "A growing number of studies have revealed that activation of the nucleotide-binding domain and leucine-rich repeat protein 3 (NLRP3) inflammasome is related to the pathogenesis of acute lung injury." (PMID 36304530, 2022). "There was increased activation of STAT6 and expression of NLRP3 in mice with murine acute lung injury (ALI)." (PMID 35606692, 2022). "The current study shows that CFH was sufficient to induce upregulation of the NLRP3 inflammasome in macrophages and that NLRP3 contributes to airspace inflammation in CFH‐induced acute lung injury." (PMID 33128438, 2020). "We aimed to elucidate the roles of the long non-coding RNA (lncRNA) maternally expressed gene 3 (MEG3)/microRNA-7b (miR-7b)/NLR pyrin domain containing 3 (NLRP3) axis in lipopolysaccharide (LPS)-induced acute lung injury (ALI)." (PMID 32852284, 2020). "The role of NOD‐like receptor protein 3 (NLRP3)‐mediated pyroptosis in acute lung injury (ALI) has been well identified previously." (PMID 33252860, 2020). "Both RIP3 necroptosis pathway and NLRP3 inflammasome pathways were examined in the mouse model of LPS-induced acute lung injury (ALI)." (PMID 30126430, 2018). "This study aimed to evaluate the potential protective effect of Ap against acute lung injury (ALI) associated with HIR, utilizing the Pringle maneuver to induce 30 min of hepatic ischemia followed by 1 h of reperfusion, while targeting the NLRP3/IL-1β signaling pathway." (PMID 41254086, 2025). "Therefore, SARS-CoV-2-induced acute lung injury (ALI)/ARDS is caused by the downregulation of ACE2, activation of the NLRP3 inflammasome and TLR2/TLR4, and autophagy." (PMID 36851766, 2023). "For example, MiR-16 could suppress NLRP3 inflammasome activation by targeting Toll-like receptor 4 directly in acute lung injury (ALI)." (PMID 36523634, 2022). "All these findings lead us to speculate that inhibition of NF-κB /NLRP3 inflammasome is the most plausible mechanism through which CB2R ameliorates the PA-induced acute lung injury and inflammation." (PMID 36463179, 2022). "Additionally, it prevents acute lung injury (ALI) by blocking NLRP3 inflammasome activation." (PMID 40012747, 2025). "P. aeruginosa infection induced acute lung injury (ALI) has also been found to be dependent, at least partially, on NLRP3 activation." (PMID 37845329, 2023). "Acute lung injury (ALI) is driven by pro-inflammatory cytokines produced by the innate immune system, which involves the nod-like receptor 3 (NLRP3) inflammasome and nuclear factor-κB (NF-κB) pathways." (PMID 35281058, 2022). "Diosmetin protects against LPS-induced acute lung injury (ALI) via increasing the expression of Nrf2 along with its target gene HO-1 and blocked the activation of NLRP3 inflammasome both in vivo and in vitro." (PMID 35242278, 2022). "Moreover, NLRP3 inflammasome activation by mtROS plays a significant role in pathogenesis of exaggerated inflammation and targeting mtROS-NLRP3 inflammasome axis may be a promising strategy for alleviating lung injury and treating acute lung injury (ALI) /acute respiratory distress syndrome (ARDS)." (PMID 37798799, 2023).
acute lung injury (continued). "Together, these data demonstrate that CFH can stimulate the NLRP3 inflammasome in macrophages and that this pathway may be important in the pathogenesis of CFH‐induced acute lung injury." (PMID 33128438, 2020). "However, whether HSF1 is involved in the activation of the NLRP3 inflammasome in septic acute lung injury (ALI) has not been reported." (PMID 35720321, 2022).
Muckle-Wells syndrome (65 papers, 2007 to 2026). "A gain-of-function mutation in the NLRP3 gene leads to cryopyrin-associated periodic fever syndrome and Muckle-Wells syndrome." (PMID 40835597, 2025). "The mutations in the NLRP3 gene are associated with the familial cold autoinflammatory syndrome, muckle wells syndrome, neonatal-onset multisystem inflammatory disease, chronic infantile neurological cutaneous, and articular syndrome." (PMID 38421496, 2024). "Mutations in NLRP3 are frequently found in patients with autoinflammatory diseases, including neonatal-onset multisystem inflammatory disease and Muckle-Wells syndrome." (PMID 29786072, 2019). "This study identified a mutation in the NLRP3 gene causing the autosomal dominantly inherited autoinflammatory Muckle-Wells syndrome." (PMID 22146561, 2011). "These conditions include Familial Cold Autoinflammatory Syndrome (FCAS) and Muckle-Wells Syndrome (MWS) caused by mutations in the CIAS1 gene (NLRP3) which encodes cryopyrin." (PMID 35003136, 2021). "The p.E313K mutation in NLRP3 has been previously reported to be associated with inherited autoinflammatory disease Muckle-Wells Syndrome (MWS)." (PMID 27965898, 2016). "In a murine NLRP3 gain-of-function model of Muckle-Wells syndrome, MCC7840 effectively inhibited mortality and demonstrated superior potency compared with MCC950." (PMID 41099134, 2026). "This is underscored by our demonstration that targeting ZBTB16 limits pathogenesis in a mouse model of Muckle-Wells syndrome, which is driven by a hyperactive mutant NLRP3." (PMID 38123560, 2023). "Somatic NLRP3 mutations can be acquired in bone marrow myeloid progenitor cells; in rare cases they can cause adult-onset CAPS, that presents with neutrophilic urticaria, fever, conjunctivitis, and arthralgia." (PMID 32983099, 2020). "Both, MCC950 and BHB, were used in a mouse model of Muckle-Wells syndrome, which is characterized by chronic inflammation mediated by NLRP3." (PMID 30356809, 2018). "BHB also reduced caspase-1 activation and IL-1β secretion in mouse models of NLRP3-mediated chronic inflammatory diseases like Muckle-Wells syndrome." (PMID 30356809, 2018). "Autosomal-dominant, heterozygous GOF mutations in NLRP3 cause the disease-severity spectrum of the predominantly familial cold induced autoinflammatory syndrome (FCAS), Muckle Wells syndrome (MWS), and the mostly sporadic severe phenotype Neonatal-onset Multisystem Inflammatory Disease (NOMID)." (PMID 32983099, 2020). "Whole exome sequencing, however, identified a p.E313K mutation in NLRP3, a gene reported to cause syndromic deafness Muckle-Wells Syndrome (MWS) but not included in any targeted NGS panels for deafness in previous reports." (PMID 27965898, 2016).